RNF180 (ring finger protein 180)
Diseases named in the same sentence as RNF180 in open-access papers (continued):
Sharing a sentence is not in itself a finding about the gene and the disease.
gastric cancer (continued). "Therefore, finding an inhibitor that targets RNF180 could potentially inhibit the progression of gastric cancer from multiple angles." (PMID 39048965, 2024). "In addition, the expression and function of BCL6 in gastric cancer could be strengthened by the RNF180/RhoC pathway." (PMID 37060074, 2023). "Therefore, the demethylation of CpG-116, CpG-80, CpG+97, and CpG+102 could increase the transcriptional level of RNF180 in gastric cancer cells." (PMID 27223257, 2016). "Thus, among patients who were already suffering from AG, an RNF180 PM average rate > 0.316 could be considered an indicator of high likelihood of gastric cancer, and of a need for intervention or treatment." (PMID 27050149, 2016). "Therefore, the methylated status of the CpG+102 island in RNF180 DNA promoter could be a promising molecular therapy to inhibit the malignant characteristics of gastric cancer cells." (PMID 27223257, 2016). "Furthermore, the promoter methylation of RNF180 DNA, which directly mediates RNF180 transcription silencing, may alter the malignant biological characteristics of gastric cancer cells to accelerate gastric cancer progression." (PMID 27223257, 2016). "In addition to the methylated status of CpG+102 island, the methylated status of CpG+97 island could be considered as another important locus in the RNF180 DNA promoter to predict the malignancy of gastric cancer cells." (PMID 27223257, 2016). "Therefore, we thought that RNF180, as a member of E3 ubiquitin ligases, might take part in above molecular events to promote the lymph node metastasis from gastric cancer." (PMID 24833402, 2014). "Although the methylation detection of RNF180 and SFRP2 shows potential for diagnosing gastric cancer, further technical optimization is necessary to ensure the reproducibility and stability of the assay." (PMID 39541711, 2024). "Furthermore, the positive co-expression of RNF180 and PCDH10 is associated with a favorable clinical prognosis in gastric cancer patients, suggesting that PCDH10 and RNF180 could be potential biomarkers for gastric cancer diagnosis." (PMID 39048965, 2024). "The E3 ligase RNF180 ubiquitinates DNMT1, significantly reducing PCDH10 methylation levels and increasing its expression in gastric cancer." (PMID 39048965, 2024). "It has been shown that RNF180 and SFRP2 are hypermethylated in gastric cancer, and our study supports this finding." (PMID 39541711, 2024). "Future studies should further explore the combination of RNF180 and SFRP2 with traditional tumor markers or other biomarkers to enhance the accuracy of gastric cancer diagnosis." (PMID 39541711, 2024). "Therefore, methylated RNF180 may serve as a candidate biomarker for gastric cancer." (PMID 38318978, 2024). "RNF180 ubiquitinates DNMT3A, markedly reducing ADAMTS9 methylation levels and increasing its expression in gastric cancer." (PMID 39048965, 2024). "According to our previous studies, RNF180 is a suppressor gene that inhibits LN metastasis in GC and could act as an independent prognostic indicator of gastric cancer." (PMID 33931579, 2021). "RING finger protein 180 (RNF180), a RING finger motif containing protein identified in 2008, has been shown to display tumor suppressive roles in gastric cancer." (PMID 33553163, 2020). "Promoter methylation of RNF180, DAPK1 and SFRP2 can be detected in plasma DNA of patients with gastric cancer." (PMID 28418867, 2017). "We proposed to investigate various CpG islands in the RNF180 DNA promoter to reveal the key locus of the methylated fragment in the promoter, which could potentially mediate the malignant biological behavior of gastric cancer cells, in a manner similar to the definition of CIMP in tumors." (PMID 27223257, 2016). "Methylated RNF180 DNA was detected in the plasma of 56% of gastric cancer patients but not in healthy controls." (PMID 39625546, 2024).
gastric cancer (continued). "Promoter methylation of RNF180 was detected in 76% of primary gastric cancers and 55% of intestinal metaplasia but in none of 23 normal gastric tissues." (PMID 39625546, 2024). "Promoter methylation of RNF180 was detected in 76% (150 of 198) of primary gastric cancers and in 55% (11 of 20) of intestinal metaplasia but in none of 23 normal gastric tissues." (PMID 33825941, 2021). "Gastric cancer cells have low expression of the RING finger E3 ligase, RNF180, which targets RhoC." (PMID 32915198, 2020). "Thus, RNF180 may be a potential candidate for GC treatment, illustrating that RNF180 has an important role in gastric cancer and its propagation by modulating the phosphorylation state of STAT3." (PMID 33082325, 2020). "In this study, we detected the quantitative methylation of RNF180 promoter and RNF180 mRNA expression simultaneously in gastric cancer and paired non-tumor tissues." (PMID 27050149, 2016). "RNF180 protein expression was also detected in 67 gastric cancer tissues and 67 paired adjacent non-tumor tissues by Western blot, simultaneously." (PMID 24833402, 2014). "Unlike the previous study, we adopted the BGS method with no less than five clones of each gastric cancer sample for enhancement the detection accuracy of the methylation of CpG sites of RNF180 promoter in this study." (PMID 24833402, 2014). "In this study, we detected the differences of RNF180 expression in gastric cancer and paired adjacent non-tumor tissues with protein and mRNA detection methods." (PMID 24833402, 2014). "RNF180 mRNA expression was detected in 67 gastric cancer tissues and 67 paired adjacent non-tumor tissues." (PMID 24833402, 2014). "RNF180 mRNA expression in paired adjacent non-tumor tissues was about 3.60-fold higher than that in gastric cancer tissues." (PMID 24833402, 2014). "Further, RNF180 hypermethylation was detected in the 76% of gastric cancer tissues, but not in normal controls, indicating that RNF180 methylation is a common event in gastric cancers." (PMID 24833402, 2014). "RNF180 protein expression in paired adjacent non-tumor tissues was about 3.56-fold higher than that in gastric cancer tissues." (PMID 24833402, 2014). "With the MSP analysis, we found 67.16% (45/67) gastric cancer tissues presented with RNF180 promoter methylation and none of 25 normal gastric mucosal tissues presented with RNF180 promoter methylation." (PMID 24833402, 2014). "These gene transcription detection results suggested that the methylation of CpG+102 island of RNF180 promoter may enhance the malignant biological characteristics of MGC-803 cells and contribute to the progression of gastric cancer, including lymphatic invasion." (PMID 27223257, 2016). "Therefore, we demonstrated that the positive rate of RNF180 protein expression in gastric cancer tissues was significantly lower than that in adjacent non-tumor tissues (P <0.001)." (PMID 24833402, 2014). "In addition, the mRNA expressive level of RNF180 was also demonstrated to be much lower in gastric cancer tissues than that in paired adjacent non-tumor tissues." (PMID 24833402, 2014). "However, we could not exclude completely the congenerous effects of other CpG sites of RNF180 promoter contributing to the progression of gastric cancer owing to no methylated CpG site in normal gastric mucosal tissues." (PMID 24833402, 2014). "Currently, no systematic studies have examined the combination of RNF180 and SFRP2 for gastric cancer diagnosis, nor has the effect of different models on sensitivity been investigated." (PMID 39541711, 2024). "RNF180 was not expressed in AGS, Kato III, MKN28, N87 and SNU1 gastric cancer cell lines." (PMID 33825941, 2021).
atrophic gastritis (2 papers, 2016 to 2017). "Although the PM status of RNF180 is known to affect GC prognosis; however, its effect on risk of GC, or on its most important precancerous state, atrophic gastritis (AG), remain unclear." (PMID 27050149, 2016).
colorectal cancer (2 papers, 2020 to 2023). A primary or metastatic malignant neoplasm that affects the colon or rectum. "Our studies revealed that Ring Finger Protein 180 (RNF180) was downregulated in a wide range of cancers, including colorectal cancer (CRC)." (PMID 33553163, 2020).
lung carcinoma (2 papers, 2022 to 2023). "To date, this is the first study to demonstrate the antitumor function of RNF180 in lung cancer and indicated its potential values as a target in NSCLC therapy." (PMID 35598017, 2022). "Moreover, our present findings not only enhanced the understanding of RNF180 as an anti-oncogene in the progression of lung cancer but also provided evidences to indicate its potential role and molecule pathway as a potential target in developing the therapy for human lung cancer." (PMID 35598017, 2022).
lymph node metastasis (2 papers, 2014 to 2016). "Approximately half of patients with eight or more methylated CpG sites of RNF180 promoter presented with the extragastric lymph node metastasis, which was an important reason for explanation the poor survival of these patients." (PMID 24833402, 2014). "Another important finding of this study is the significant correlation between the methylated CpG site of RNF180 promoter and lymph node metastasis." (PMID 24833402, 2014).
ovarian carcinoma (2 papers, 2024 to 2025). A malignant neoplasm originating from the surface ovarian epithelium. "RNF180 is involved in various physiological processes, including cell growth, differentiation, and tumorigenesis Several studies have shown that RNF180 is silenced or downregulated in a variety of cancers, including gastric, colorectal, and ovarian cancers." (PMID 39541711, 2024). "The tumor suppressor RNF180 and its downstream target IPO4 have been validated in ovarian cancer models, forming a crucial molecular regulatory network." (PMID 41154754, 2025).
colorectal tumor (1 paper, 2020). "Focusing on colorectal tumor samples, we confirmed that RNF180 was downregulated in TCGA colorectal tumor samples compared to normal colorectal tissues." (PMID 33553163, 2020).
gastritis (1 paper, 2016). Inflammation of the stomach. "H.pylori affects RNF180 PM in normal tissue or mild gastritis, and increases hypermethylation in 3 CpG sites in AG." (PMID 27050149, 2016). "Our results, together with those of previous reports, indicate that H.pylori infection can increase overall methylation in normal or slightly superficial gastritis tissues, but after AG develops, H.pylori can increase hypermethylation at M3(−165), M25(−34) and M30(+5) in the RNF180 promoter region." (PMID 27050149, 2016).
metastasis (1 paper, 2014). The spread or migration of cancer cells from one part of the body (where they first appeared) to another. "However, the methylation levels of the RNF180 gene were found to positively correlate with tumor size (P=0.018), histological type (P=0.025), TNM stage (P=0.002), lymph node metastasis (P=0.008) and distant metastasis (P=0.018)." (PMID 25202403, 2014).
metastatic tumors (1 paper, 2020). "It seems to be a promising cure for the metastatic tumors to develop small molecule inhibitors for RNF180 to target RNF180-decreased RhoC." (PMID 33082325, 2020).
osteosarcoma (1 paper, 2025). A usually aggressive malignant bone-forming mesenchymal neoplasm, predominantly affecting adolescents and young adults. "In osteosarcoma, the upregulation of RNF180 augments the ubiquitination of CBX4, consequently diminishing CBX4 expression in cells." (PMID 40148674, 2025).
tumor (21 papers, 2014 to 2025). "DNMT1 overexpression and low expression of RNF180 were associated with poor prognosis and aggressive tumor behavior." (PMID 37147733, 2023). "RNF180 is an E3 ubiquitin ligase that functions as a tumor suppressor by inhibiting growth, proliferation, and migration in GC cells, but can have pro-tumorigenic effects when hypermethylated." (PMID 37840147, 2023). "Our previous studies showed that RNF180, a tumor suppressor in GC, inhibited the proliferation and movement of GC cells." (PMID 37060074, 2023). "Further, experiments on animals and cell lines suggest that RNF180 inhibits the proliferation, migration, and invasion of GC cells and inhibits tumor growth and lymphangiogenesis." (PMID 36246966, 2022). "In 93 patients, we observed 53 tumorous tissues exhibiting high level of RNF180 expression, where the number of 40 tissues with were identified with low level of RNF180 expression." (PMID 35598017, 2022). "Together, these results firstly indicated the anti-tumor properties of RNF180 and its correlation with NSCLC progression, thereby endorsing the potential role of RNF180 as an efficient prognostic biomarker for tumor recurrence." (PMID 35598017, 2022). "Ring finger protein 180 (RNF180) is a tumor suppressor gene located on the long arm of chromosome 5." (PMID 36703788, 2022). "In fact, when compared to the sensitivity of various other tumor indicators, the RNF180 gene methylation assay performs admirably." (PMID 36703788, 2022). "Next, IHC assay was used to examine the protein expression of RNF180 in tumor tissues and para-cancerous." (PMID 35598017, 2022). "As a tumor suppressor gene, RNF180 is involved in a variety of physiological and pathological processes and plays an important role in cell signal transduction, apoptosis, gene transcription, and DNA repair by mediating protein degradation." (PMID 36246966, 2022). "We measured the protein expression levels of RNF180 and RhoC in 113 pairs of tumor and adjacent non-tumor tissues by IHC." (PMID 33082325, 2020). "Correspondingly, tumor weights displayed similar results, with the 5-FU+RNF180 high group showing smallest tumors." (PMID 33553163, 2020). "Our findings revealed a crucial role of RNF180 in suppressing tumor growth by ubiquitinating WISP1 in CRC." (PMID 33553163, 2020). "Using the CRC PDX mouse, we demonstrated that 5-FU significantly reduced tumor burden in the group with higher RNF180 expression." (PMID 33553163, 2020). "Based on our analyses of the anti-tumor activity of RNF180, we found that RNF180 inhibited the expression of the WISP1 oncoprotein by promoting WISP1 ubiquitination, thereby suppressing tumor growth." (PMID 33553163, 2020). "Correspondingly, tumor weights exhibited the same pattern, with RNF180+WISP1 mice exhibiting intermediate tumor size." (PMID 33553163, 2020). "The mRNA expressive level of RNF180 was demonstrated to be significantly lower in tumor tissues than that in non-tumor tissues, and with the same tend as which in hypermethylation tissues than that in hypomethylation tissues." (PMID 27050149, 2016). "The expression of RNF180 mRNA levels in tumor were significantly lower than those in non-tumor, with the same as in hypermethylation than hypomethylation group." (PMID 27050149, 2016). "RNF180 acts as a potential tumor suppressor, exhibiting a critical role in the suppression of cell proliferation and induction of apoptosis." (PMID 25202403, 2014). "RNF180 protein expression was detected in 38 (56.72%) (−), 13 (19.40%) (+), 10 (14.92%) (++), and 6 (8.96%) (+++) tumor samples, which represented that only 16 (23.88%) patients presented positive RNF180 protein expression." (PMID 24833402, 2014). "Meanwhile, we found that 7 (10.45%) (−), 21 (31.34%) (+), 19 (28.36%) (++), and 20 (29.85%) (+++) of RNF180 protein expression were detected in paired adjacent non-tumor tissues, respectively." (PMID 24833402, 2014).
tumor (continued). "In conclusion, BCL6 expression and its tumor suppressor role in GC could be strengthened by RNF180/RhoC pathway." (PMID 37060074, 2023). "Similarly, RNF180 (mRNF180) methylation levels were significantly higher in GC tumor tissues compared with that in adjacent non-tumor tissues." (PMID 37840147, 2023). "When RNF180 was methylated, it led to structural and functional alterations in the gene that made it less effective at promoting apoptosis and failed to stop the growth, differentiation, and metastasis of the tumor." (PMID 36703788, 2022). "As a tumor suppressor, RNF180 could restore the activity of some tumor-related genes, including ADAMTS9, and played a crucial role in impairing lymphatic involvement of GC cells." (PMID 33931579, 2021). "RNF180 is an E3 ubiquitin ligase that belongs to the ubiquitin-proteasome system and plays an important role in post-translational modification, which actually influence several processes of oncogenesis and tumor progression." (PMID 33931579, 2021). "Taken together, these results suggest that RNF180 may function as a tumor suppressor in the pathogenesis of CRC." (PMID 33553163, 2020). "RNF180 protein expression in GC tissues was identified as an independent predictor of outcome (hazard ratio [HR] 0.628; P = 0.006), pN stage (HR 1.258; P = 0.005) and tumor location (HR 1.275; P = 0.015)." (PMID 33082325, 2020). "Collectively, these results support that RNF180 played tumor suppressive functions." (PMID 33553163, 2020). "In contrast, RNF180 overexpression significantly reduced tumor volume." (PMID 33553163, 2020). "Last, 5-FU and RNF180 had synergetic effect on the apoptosis induction and tumor growth inhibition." (PMID 33553163, 2020). "Moreover, WISP1 was found to be the critical downstream molecule that mediated the tumor suppressive effects of RNF180." (PMID 33553163, 2020). "In addition, 5-FU and RNF180 had synergetic effect on the apoptosis induction and tumor growth inhibition of CRC cells in vitro and in vivo." (PMID 33553163, 2020). "Furthermore, 5-FU and RNF180 had synergetic effect on the apoptosis induction and tumor growth inhibition of CRC, suggesting a novel therapeutic strategy for CRC treatment." (PMID 33553163, 2020). "In summary, our findings suggest that RNF180 could reduce tumor metastasis in GC by inhibiting STAT3 activation via RhoC protein degradation through the ubiquitin–proteasome system." (PMID 33082325, 2020). "Consistently, lower expression of RNF180 resulted in increased tumor volume in vehicle groups." (PMID 33553163, 2020). "The aberrant expression of RNF180 mRNA levels in tumor might be resulted from the DNA promoter methylation." (PMID 27050149, 2016). "Notably, RNF180 methylation was found to positively correlate with tumor size (P=0.018), histological type (P=0.025), TNM stage (P=0.002), lymph node metastasis (P=0.008) and distant metastasis (P=0.018)." (PMID 25202403, 2014). "The CpGs constituting the FCC were primarily associated with the two known aging genes ELOLV2 and KLF14, linked to metabolism, which were hypermethylated, followed by a tumour suppressing gene RNF180, and DYTN, a gene with unknown function, that were both hypomethylated." (PMID 39695947, 2024). "The methylation of the CpG+102 island in RNF180 DNA promoter could promote tumor progression by regulating the malignant biological abilities of MGC-803 cells, including proliferation, invasion, cell cycle, and anti-apoptosis, and by promoting the tumorigenicity of MGC-803 cells in vivo." (PMID 27223257, 2016). "To improve the sensitivity of detecting GC, we included 78 GC patients and 124 healthy individuals in the training set and divided them into three groups: RNF180 and SFRP2 (RS), a tumor marker group (CEA, CA125, and CA199), and a group with RS + tumor marker." (PMID 39541711, 2024).